TTYH1 (tweety family member 1)
Diseases named in the same sentence as TTYH1 in open-access papers (continued):
Sharing a sentence is not in itself a finding about the gene and the disease.
Strabismus (1 paper, 2021). A misalignment of the eyes so that the visual axes deviate from bifoveal fixation. "As a result, we found risk variants in four genes (FAT3, KCNH2, CELSR1, and TTYH1) in five families, suggesting their role in development of familial strabismus." (PMID 33435129, 2021). "Despite the small sample study, we were able to identify four genes (FAT3, KCNH2, CELSR1, TTYH1) with causative associations with strabismus." (PMID 33435129, 2021).
tumor (14 papers, 2017 to 2025). "At the gene expression level, NLGN3 induces the upregulation of TTYH1 gene, which enhances synapse-associated gene expression, tumor microtube formation and growth." (PMID 38473812, 2024). "However, although Ttyh1 expression is important for TMs formation, Ttyh1-deficient cells with more than two TMs showed higher TMs interconnectivity, leading to increased RR of tumor cells." (PMID 34900673, 2021). "This is because in bipolar tumor cells, TTYH1 colocalizes with chloride-ion channels and integrin-α5 molecules, which control cell volume and navigation through neuropil and the ECM." (PMID 38473812, 2024). "In addition, recent identification of Tweety family member 1 (TTYH1):C19MC gene fusions in embryonal tumours with multi-layered rosettes (ETMRs) have been identified and observed to be associated with very high expression of specific miRNAs." (PMID 28103887, 2017). "TTYH1 knockdown decreased the rate of invasive tumour cells harboring one or two TM but not the rate of hyperconnected cells harboring more than four TM, unveiling a functional and molecular heterogeneity among TM." (PMID 38834748, 2024). "Interestingly, this knockdown of Ttyh1 did not significantly impact TM‐connected tumour cells, highlighting a specific role for Ttyh1 in non‐connecting TMs and their invasive properties." (PMID 38567664, 2024). "Moreover, TTYH1 knockdown caused formation of dysfunctional TMs that exhibited poor invasion and proliferation, suggesting that TTYH1 drives tumor invasiveness but not connectivity." (PMID 38473812, 2024).
cancer (7 papers, 2019 to 2022). A tumor composed of atypical neoplastic, often pleomorphic cells that invade other tissues. "Therefore, it is worth investigating whether gene deficiency of TTYH1 or TTYH2 is associated with the cisplatin resistance in these cancer cells." (PMID 31181821, 2019). "In these cancer cells, TTYH1 and TTYH2 regulate cell proliferation and migration, which can be effectively inhibited by silencing the corresponding gene." (PMID 31181821, 2019). "We investigated whether TTYH1 expression levels correlate with the increase in the cancer progression-related properties of U2OS cells." (PMID 35455021, 2022). "A subsequent study has assigned an equivalent function to TTYH1 and 2 in cancer cells." (PMID 34385445, 2021). "Therefore, the functional roles of TTYH1- or TTYH2-mediated VRAC currents should be examined in these cancer cells." (PMID 31181821, 2019). "In addition, we examined the expression of TTYH1 or TTYH2 in several cancer cell lines and found that VRAC currents of these cells were abolished by gene silencing of TTYH1 or TTYH2." (PMID 31181821, 2019). "We found that TTYH1 or TTYH2 could act as VRACs in cancer cells (SNU-601, HepG2, and LoVo cells), and that these channels were not expressed in MCF-7 cells." (PMID 31181821, 2019). "Based on the gene expression profiles of these three types of cells (VRAC-active, VRAC-deficient, and VRAC-restored), we selected two candidate VRAC genes, TTYH1 and TTYH2, and confirmed that the channels they encode can act as VRACs in several types of cancer cells." (PMID 31181821, 2019). "Recently, the TTYH1 and TTYH2 subunits have been identified as novel components of VRAC in some cancer cells." (PMID 35054564, 2021). "A fourth study attributed endogenous anionic currents in SNU-601, HepG2, and LoVo cancer cells to TTYH2 and/or TTYH1 channel activity." (PMID 34824283, 2021). "Taken together, these results suggest that TTYH1 and TTYH2 function independently as VRACs in various cancer cells." (PMID 31181821, 2019). "To establish the VRAC activity of TTYH1 and TTYH2, we investigated other cancer cell lines that endogenously express these two channels." (PMID 31181821, 2019). "Although leucine-rich repeat–containing 8A (LRRC8A) has been characterized as a molecular component of VRACs, here we show that Drosophila melanogaster tweety homologue 1 and 2 (TTYH1 and TTYH2) are critical for VRAC currents in cancer cells." (PMID 31181821, 2019). "Taken together, our data clearly show that TTYH1 and TTYH2 can act as LRRC8A-independent VRACs, suggesting novel therapeutic approaches for VRACs in cancer cells." (PMID 31181821, 2019). "Additionally, we observed that TTYH1 effectively regulated the protein expression levels of MMP-2/9 and N-cadherin, which are involved in the migration and invasion of cancer cells." (PMID 35455021, 2022). "A caveat when comparing pathological to normal tissues and cells is that RNA-Seq and microarray experiments demonstrate how TTYH1 and TTYH2 expression patterns and cancers may be cell and tissue-type-dependent." (PMID 34262434, 2021). "These binding partners of TTYH1 or TTYH2 may be involved in the regulatory mechanisms of VRACs in diverse normal tissues and cancer cells." (PMID 31181821, 2019).
TTYH1 also shares sentences with these, for which no sentence is quoted: brain cancer (2 papers); medulloblastoma (2); triple-negative breast carcinoma (2); amyotrophic lateral sclerosis (1); Anxiety (1); liver cancer (1); rhabdoid tumor (1); sarcoma (1); Seizure (1); serous ovarian carcinoma (1); tongue cancer (1).